SCART1 (scavenger receptor family member expressed on T cells 1)
Description:
May play a role in the immune system, perhaps as a co-receptor on alphabeta and gammadelta T-cells.
Synonyms: CD163c-alpha
Tractability: Antibody: UniProt predicts a signal peptide or a membrane-spanning region; its Gene Ontology location is reachable by antibodies, with medium confidence.
Gene: Protein-coding gene on chromosome 10 (133,453,928 to 133,523,558, forward strand). Ensembl gene ENSG00000214279.
Subcellular location: Membrane
Gene Ontology:
Molecular function: scavenger receptor activity
Biological process: gamma-delta T cell lineage commitment; T cell mediated immunity; vesicle-mediated transport
Cellular component: brush border; cytoplasm; plasma membrane; membrane
Homologues: Orthologues: chimpanzee SCART1 (77% identical), pig SCART1 (67% identical), dog SCART1 (61% identical), mouse Scart2 (52% identical), rat Or12j2 (51% identical). Paralogues in human: CD163L1 (34% identical), CD163 (33% identical), DMBT1 (31% identical), SSC5D (28% identical), PRSS12 (19% identical), SSC4D (17% identical), LOXL2 (16% identical), LOXL3 (15% identical), LOXL4 (15% identical), CD6 (14% identical), CD5L (14% identical), CD5 (10% identical), and 3 more.
Diseases named in the same sentence as SCART1 in open-access papers:
SCART1 is named in the same sentence as 5 diseases in open-access papers, as found by Europe PMC text mining. Sharing a sentence is not in itself a finding about the gene and the disease. The quoted sentences say what the papers report.
pneumonia (4 papers, 2023 to 2025). An acute, acute and chronic, or chronic inflammation focally or diffusely affecting the lung parenchyma, caused by an infection in one or both of the lungs (by bacteria, viruses, fungi, or mycoplasma.). "The immune genes’ mRNA levels in goats (SLC11A1, CD-14, CCL2, TLR1, TLR7, TLR8, TLR9, defensin, SP110, SPP1, BP1, A2M, ADORA3, CARD15, IRF3, and SCART1) varied between the healthy and infected goats with pneumonia." (PMID 40711280, 2025). "In our opinion, this is the first study to identify SNPs in antioxidant (SOD1, CAT, GPX1, NOS, HMOX1, and NQO1) and immunological (IL-1α, IL1B, IL6, TNF-α, IL10, LFA-1, CR2, IL17, IL13, DEFB123, SCART1, and ICAM1) genes as potential suspects for pneumonia resistance/susceptibility in Barki ewes." (PMID 40221769, 2025). "In Baladi goats with pneumonia and healthy control group, PCR-DNA sequencing revealed SNPs linked to pneumonia susceptibility and resistance in immunological genes (SLC11A1, CD-14, CCL2, TLR1, TLR7, TLR8, TLR9, defensin, SP110, SPP1, BP1, A2M, ADORA3, CARD15, IRF3, and SCART1)." (PMID 40221769, 2025). "The levels of immunological genes (SLC11A1, CD-14, CCL2, TLR1, TLR7, TLR8, TLR9, defensin, SP110, SPP1, BP1, A2M, ADORA3, CARD15, IRF3, and SCART1) vary in goats with and without pneumonia." (PMID 40221769, 2025). "Real-time PCR was conducted to quantify the expression levels of immunological markers (SLC11A1, CD-14, CCL2, TLR1, TLR7, TLR8, TLR9, β defensin, SP110, SPP1, BP1, A2M, ADORA3, CARD15, IRF3, and SCART1) in Baladi goats with and without pneumonia resistance." (PMID 36977224, 2023). "Through PCR-DNA sequencing in Baladi goats with and without pneumonia, SNPs linked to pneumonia susceptibility and resistance were discovered in the immunological (SLC11A1, CD-14, CCL2, TLR1, TLR7, TLR8, TLR9, defensin, SP110, SPP1, BP1, A2M, ADORA3, CARD15, IRF3, and SCART1) genes." (PMID 40711280, 2025).
craniosynostosis (1 paper, 2025). Craniosynostosis is defined as the premature fusion of one or more cranial sutures leading to secondary distortion of skull shape resulting in skull deformities with a variable presentation. "The SCART1 and SYCE1 genes have no published research associated with craniosynostosis, bone homeostasis or any of the pathways investigated in the study." (PMID 40843495, 2025).
food allergy (1 paper, 2022). Gastrointestinal disturbances, skin eruptions, or shock due to allergic reactions to allergens in food. "RUFY1, in context of aero‐allergens, presented in a different methylation direction between the studies, while SCART1, in context of food allergy, did not." (PMID 36225266, 2022).
Krebs 2 carcinoma (1 paper, 2022). "The obtained data confirmed the strong overexpression of Mreg, Prg4, Col3a1, Selp, Marco, and Fgfr1 genes in Krebs-2 carcinoma, as well as Cdh11, Col4a5, Vcam1, Megf6, Scarf2, Scart1, and Cd14 genes in HH47." (PMID 36555446, 2022).
skin inflammation (1 paper, 2017). "It was reported that Scart1+ γδ TCR+ cells infiltrate both the dermis and epidermis in 12-O-tetradecanoyl-phorbol-13-acetate (TPA)-induced skin inflammation model." (PMID 28081153, 2017).